SATB1 (SATB homeobox 1)
Diseases named in the same sentence as SATB1 in open-access papers (continued):
Sharing a sentence is not in itself a finding about the gene and the disease.
breast carcinoma (continued). "SATB1 and HER2 performed a synergistic effect in breast cancer." (PMID 25956130, 2015). "It was reported that the expression of SATB1 was higher in poorly differentiated than in well differentiated breast cancer and completely absent in adjacent normal tissues." (PMID 25956130, 2015). "The objectives of this study were to assess the correlations of SATB1 expression with HER2 and HR expression in breast cancer tissues, and to evaluate the effects of SATB1 expression on HER2 and HR expression as well as their relationships with clinicopathologic characteristics." (PMID 25956130, 2015). "In breast cancer, SATB1 expression was found not restricted to advanced clinical stages of disease, and the SATB1 level had high prognostic significance in breast cancer, independent of the lymph node status." (PMID 24971456, 2014). "Importantly, SATB1565–574 peptide-specific T cells recognized and killed HLA-A*02+ SATB1-expressing Jeko-1, Skov-1 cells as well as IFN-γ-treated breast cancer cell lines (CAMA-1 and MDA-MB-231), suggesting this peptide is naturally processed by cancer cells." (PMID 23437226, 2013). "We next focused our attention exclusively on SATB1, CCND2 and FSCN1 as mediators of miR-191 and miR-425 effects, respectively, because of their strong repression obtained after miRNA expression and their reported tumorigenic function in breast cancer." (PMID 23505378, 2013). "Although BRCA1/2 mutations can incite genomic instability and are strong predictors of breast cancer, SATB1 abnormality is unrelated to BRCA1/2 mutations indicating that SATB1 affects DNA repair in a manner which is independent of BRCA1/2." (PMID 23326301, 2013). "SATB1 expression was shown previously to promote metastasis in established but non-metastatic breast cancer cells." (PMID 23251624, 2012). "Indeed, ATM mRNA was lower in MCF10A-1 and in several other SATB1-responsive breast cancer cell lines as compared to MCF10A-2 cells, suggesting that the level of ATM negatively correlates with the responsiveness to SATB1 overexpression." (PMID 23251624, 2012). "They found that the ectopic expression of SATB1 in non-metastatic cells, inducing invasive behaviors and SATB1 knockdown in metastatic breast cancer cells (MDA-MB-231), reversed their invasive phenotype and prevented both lung metastases and primary tumor formation in mice." (PMID 40071088, 2025). "(C) Boxplots of SATB1 gene expression: (i) subject-level rlog values in LEPs and MEPs of younger and older women; (ii) log2 values in normal breast tissue (GSE102088); and (iii) log2 FPKM values in the TCGA breast cancer cohort by PAM50 subtype in cancers and in matched normal tissue." (PMID 39545637, 2024). "Moreover, the SATB1 protein was found to be overexpressed in breast cancer specimens as compared to adjacent non-malignant breast tissues, and the high level of its expression was associated with a poor degree of tumour differentiation." (PMID 31450715, 2019). "Moreover, ectopic SATB1 expression in a nonaggressive breast cancer cell line induced the aggressive phenotype and metastatic activity in the cells." (PMID 25874491, 2015). "Interestingly, our results showed that SATB1 was expressed in the infiltrating lymphocytes within some breast cancer tissues but not in the adjacent non-malignant tissues." (PMID 25956130, 2015). "Furthermore, SATB1 was found to have a high prognostic significance in breast cancer, independent of lymph node status." (PMID 24971456, 2014). "Although SATB1565–574 peptide-specific T cells recognized and killed HLA-A*02+ SATB1-expressing Jeko-1 and Skov-1 cells, however, they did not directly recognize the other two HLA-A*02+ SATB1+ breast cancer cells tested in this study including CAMA-1 and MDA-MB-231." (PMID 23437226, 2013).
breast carcinoma (continued). "Quantitative RT-PCR and immunoblot analyses showed that endogenous SATB1 levels were very low to undetectable in all immortalized non-tumorigenic cell lines tested in contrast to its easily detectable expression in metastatic human breast cancer cell lines, MDA-MB-231 and BT549." (PMID 23251624, 2012).
colorectal cancer (33 papers, 2012 to 2025). A primary or metastatic malignant neoplasm that affects the colon or rectum. "It is important in the initiation of colorectal cancer and SATB1 expression in colorectal cancer is associated with the expression of S100A4, MMP2, NF-kB, PCNA, cyclin D1 and β-catenin." (PMID 33356851, 2020). "Baicalein and hydrophobic statins were shown to successfully down-regulate the level of SATB1 in breast and colorectal cancer cells respectively, causing a significant decrease in cells’ proliferation and invasion abilities." (PMID 31450715, 2019). "The results of this study demonstrate that SATB1 expression in colorectal cancer is significantly associated with beta-catenin overexpression, microsatellite stability and SATB2 expression." (PMID 22935204, 2012). "In colorectal cancer, loss of SATB1 was reported to be a strong predictor of worse outcomes." (PMID 27966447, 2017). "The association between SATB1 and colorectal cancer (CRC) remains unclear." (PMID 24971456, 2014). "Additionally, to determine whether SATB1 is associated with capacity for invasion in colorectal cancer cells, a cell invasion assay using matrigel and a multiporous membrane was carried out with LOVO cells in which SATB1 was down regulated." (PMID 23326301, 2013). "SATB1 expression has been demonstrated to correlate with unfavourable tumour characteristics in rectal cancer, but its association with clinical outcome in colorectal cancer (CRC) remains unclear." (PMID 22935204, 2012). "Emerging evidence indicates that Wnt/β-catenin signaling upregulates SATB1 to drive colorectal cancer initiation and progression, while PAK5-mediated phosphorylation enhances its oncogenic potential in cervical cancer." (PMID 41208974, 2025). "In breast and colorectal cancers, SATB1 was shown to interfere with the Wnt/β-catenin pathway, which is thought to be crucial for metastasis." (PMID 31450715, 2019). "The idea that SATB1 is a potential prognosis factor in gastrointestinal cancer patients stemmed from the finding that SATB1 plays a crucial role in the development of colorectal cancer, gastric cancer and other types of cancer/solid tumors." (PMID 28430598, 2017). "The median expression levels of SATB1 in esophageal, gastric, and colorectal cancer were 50.47%, 50.00%, and 46.53%, respectively." (PMID 28636989, 2017). "Our findings are also in line with a recent study in colorectal cancer, where SATB1 was found to be a target of Wnt/β-catenin signaling while in turn simultaneously regulating β-catenin expression." (PMID 28049521, 2017). "SATB1 also promotes aggressive tumor behavior in several types of neoplasms, including gastric and colorectal cancers." (PMID 28636989, 2017). "The expression levels of SATB1 in esophageal, gastric, and colorectal cancer were 50.47%, 50.00% and 46.53%, respectively." (PMID 28636989, 2017). "First we analyzed the overall influence of SATB1 expression on OS in all gastrointestinal cancer, including 6 studies of colorectal cancer, 4 studies of gastric cancer, one study of esophageal cancer and one study of pancreatic cancer." (PMID 28430598, 2017). "We next examined the effects of the transient knockdown of SATB1 on colorectal cancer cells using short interfering RNA (siRNA) transfection." (PMID 26701851, 2016). "The expression of SATB1 in colorectal cancer tissues was positively correlated with c-Myc expression, and SATB1 knockdown reduced c-Myc expression in colorectal cancer cells." (PMID 26701851, 2016). "Here, we showed that the expression of SATB1 in colorectal cancer tissues was positively correlated with c-Myc expression and that SATB1 knockdown reduced c-Myc expression in colorectal cancer cells." (PMID 26701851, 2016). "In this report, we examined the effects of SATB2 expression and SATB1 knockdown in different colorectal cancer cell lines." (PMID 26701851, 2016).
colorectal cancer (continued). "SATB1 mRNA levels were increased in the human colorectal cancer specimens (n = 20) compared to the normal controls (n = 9)." (PMID 26701851, 2016). "To investigate the function of SATB1 in colorectal cancer, we first examined SATB1 mRNA levels in human colorectal cancer tissues by qRT-PCR." (PMID 26701851, 2016). "SATB1 expression and its role in colorectal cancer have been investigated in five studies in which samples of tumor and noncancerous colorectal tissues of CRC patients were compared; however, the colon mucosa of healthy individuals was not investigated." (PMID 25874491, 2015). "Special AT-rich sequence-binding protein 1 (SATB1) is a ‘genome organizer,’ and it has been proposed as a factor that affects the development and progression of various human neoplasms, including colorectal cancer (CRC)." (PMID 25874491, 2015). "Strikingly, in this study, the effects of up- and down-regulation of SATB1 expression on malignant phenotypic features in colorectal cancer cells were both investigated." (PMID 24971456, 2014). "Kaplan-Meier estimates of colorectal cancer-specific survival according to combination of SATB1 and SATB2 expression showed that SATB1-negative/SATB2-positive and SATB1-negative/SATB2-negative groups have the better survival time." (PMID 24971456, 2014). "Other papers have reported contradicting results regarding the role of SATB1 in cancer progression in breast and colorectal cancer." (PMID 25326863, 2014). "We also studied the effect of SATB1 on apoptosis in colorectal cancer cells using flow cytometry with the Annexin V-PI kit." (PMID 23326301, 2013). "In this study, we showed over-expression of SATB1 in 80 cases of colorectal cancer and in 3 colorectal cancer cell lines and found expression levels were strongly associated with tumor differentiation and stage." (PMID 23326301, 2013). "As these proteins are important prognostic factors in colorectal cancer, this correlation with SATB1 expression additionally supports the concept SATB1 is a driver of the malignant phenotype in colorectal carcinoma." (PMID 23326301, 2013). "The results from this large, prospective cohort study of colorectal cancer demonstrate that SATB1 is expressed in a subset of colorectal carcinomas, and correlates with beta-catenin overexpression, microsatellite stable tumours and SATB2 expression." (PMID 22935204, 2012). "In colorectal cancer, miR-191-5p acts as a tumor suppressor because its endogenous induction inhibits cell proliferation and invasion through two molecular targets: special AT-rich sequence-binding protein 1 (SATB1) and tripartite motif-containing 14 (TRIM14)." (PMID 38994952, 2024). "A previous study showed that β-catenin in the nucleus combined with SATB1 could upregulate the transcriptional level of TCF7L2 in colorectal cancer." (PMID 34489551, 2021). "Colorectal cancers which exhibit elevated Wnt/Wg signaling also express SATB1 at higher levels." (PMID 33564000, 2021). "Accordingly, SATB1 promotes metastasis and cell growth in colorectal cancer." (PMID 35201514, 2021). "Moreover, it is the high expression level of SATB1 that relates to poor prognosis in colorectal cancer patients." (PMID 33356851, 2020). "Therefore, a lot of reports support the idea that SATB1 expression is a biomarker predicting the poor prognosis in colorectal cancer patients." (PMID 33356851, 2020). "Conversely, knocking down miRNA levels, so as to promote increased SATB1 expression, might be beneficial in colorectal cancer chemotherapy." (PMID 30576489, 2018). "Because SATB1 is a chromatin modifier that regulates gene expression by binding to the 5′ base-unpairing regions (BURs), future studies could uncover the molecular mechanisms of c-Myc activation by SATB1 in colorectal cancer." (PMID 26701851, 2016). "We first tested whether SATB1 knockdown inhibits the anchorage-independent growth of colorectal cancer cells." (PMID 26701851, 2016).
colorectal cancer (continued). "Our results suggest that c-Myc may be a potential therapeutic target for colorectal cancers with high expression of SATB1 or low expression of SATB2." (PMID 26701851, 2016). "Finally, we showed that SATB1 knockdown in colorectal cancer cells suppressed cell proliferation, colony formation and cell invasion." (PMID 26701851, 2016). "Thus, our observations suggest that in normal mucosa, posttranscriptional events limit the SATB1 expression, and this regulation becomes disturbed in colorectal carcinoma." (PMID 25874491, 2015). "Expression of the Special AT-rich sequence-binding protein 1 (SATB1) has been demonstrated to confer a worse prognosis in several tumour types, whereas its close homologue SATB2 is a proposed diagnostic and favourable prognostic marker for colorectal cancer." (PMID 25323550, 2014). "Recently, two studies have focused on the relationship of SATB1 with colorectal cancer." (PMID 24971456, 2014). "In conclusion, SATB1 was over-expressed in this study in colorectal cancer tissues and cell lines." (PMID 23326301, 2013). "First, it is inconclusive whether SATB1 expression correlates with OS in colorectal cancer." (PMID 28430598, 2017). "Finally, we examined the expression levels of SATB1 and c-Myc in colorectal cancer tissues." (PMID 26701851, 2016). "The association between SATB1 and colorectal cancer (CRC) has not been studied intensively." (PMID 24971456, 2014). "Similar results from silencing SATB1 were also later observed in the RKO, LS147T, HT29 and HCT116 colorectal cancer cell lines." (PMID 31450715, 2019). "In this study, we examined the effects of SATB1 and SATB2 on the malignant characteristics of colorectal cancer cells." (PMID 26701851, 2016). "The results elucidate the importance of SATB1 and SATB2 in understanding oncogenic c-Myc-induced colorectal tumorigenesis, making SATB1 a promising therapeutic target for colorectal cancer." (PMID 26701851, 2016). "SATB1 expression was increased, whereas SATB2 expression was reduced, in colorectal cancer tissues compared to control tissues." (PMID 26701851, 2016). "Further, statins treatment is known to downregulate SATB1 in colorectal cancer cells but the effect on its homolog SATB2 is not known." (PMID 40177244, 2025). "SATB1 and SATB2 expression were negatively correlated in colorectal cancer specimens." (PMID 26701851, 2016). "Better understanding of the mechanisms leading to the alterations in the control of SATB1 expression in precancerous colorectal lesions and CRC tissue may provide deeper insight into the pathogenesis of colorectal cancer." (PMID 25874491, 2015). "Future studies are needed to elucidate the potential mechanisms by which SATB1 affects colorectal cancer progression, not least its potential synergistic or antagonostic effects with SATB2." (PMID 22935204, 2012). "SATB1 expression levels have been examined in tumor and unchanged tissue samples of patients suffering from rectal or colorectal cancer, but so far, there was no comparison of the level of SATB1 expression in CRC tissue and normal colon mucosa of healthy subjects." (PMID 25874491, 2015). "SATB1 immunoreactivity was limited to a subpopulation of lymphoid cells in various tissues, but no immunoreactivity was observed in glandular cells in the rectum, colon, or in colorectal cancer (data not shown)." (PMID 25326863, 2014).
gastric cancer (23 papers, 2011 to 2025). A primary or metastatic malignant neoplasm involving the stomach. "SATB1 overexpression is also linked to EMT promotion in gastric cancer, characterized by increased N-cadherin and Vimentin, along with reduced CDH1, correlating with advanced disease and lymph node metastasis." (PMID 40071088, 2025). "An elevated SATB1 expression in gastric cancer specimens, as well as its association with an advanced TNM stage and the presence of distant metastasis, was also observed by Yuan and colleagues." (PMID 31450715, 2019). "Increasing evidence indicated that SATB-1 upregulation was also closely associated with poor prognosis in other malignancies, such as prostate, ovarian, and gastric cancers, as well as in hepatocellular and renal cell carcinomas." (PMID 30337520, 2018). "SATB1 expression in gastric cancer has previously been examined in two studies on Chinese populations, both indicating that SATB1 expression is independently associated with worse prognosis." (PMID 25326863, 2014). "SATB1 overexpression has also been associated with poor prognosis in laryngeal squamous cell carcinoma, gastric cancer, and malignant cutaneous melanoma." (PMID 24971456, 2014). "Supporting the role of SATB1 in promoting metastasis, SATB1 expression has been associated with the development and metastasis of bladder urothelial carcinoma and gastric carcinoma." (PMID 24212802, 2011). "Furthermore, SATB1 has been implicated in the regulation of multidrug resistance (MDR) in gastric cancer, contributing to poor chemotherapy responses and worse outcomes." (PMID 40071088, 2025). "Finally, subgroup analysis of association between SATB1 and OS in gastric cancer only included 4 studies, three of which were carried out in Asian population." (PMID 28430598, 2017). "Interestingly, our subgroup analysis based on tumor type revealed that gastric cancer with invasion and metastasis was the type most closely linked with SATB1 overexpression." (PMID 28636989, 2017). "Furthermore, our research is the first to show that gastric cancer is the tumor type most closely linked with SATB1 overexpression." (PMID 28636989, 2017). "PAK2 was a necessary interaction partner of ARHGDIB, and knockdown of PAK2 greatly reduced ARHGDIB-induced cell invasion and ARHGDIB-mediated chemoresistance in gastric cancer, and loss of SATB1 in lung cancer has been shown as a possible marker for poor survival." (PMID 24369726, 2013). "Hence, Heparanase could have a promoting role in gastric cancer spread, and therefore SATB1 could be associated with gastric cancer dissemination." (PMID 31450715, 2019). "SATB1 is significantly overexpressed in gastric cancer tissues compared with normal gastric mucosa, with high SATB1 expression associated with poor survival, local invasion, lymph node metastasis, and advanced TNM stages." (PMID 40071088, 2025). "SATB1 is implicated in the upregulation of HER3 expression following MET inhibition, enhancing HRG/HER3 signaling and thereby allowing gastric cancer cells to evade the cytotoxic effects of MET-targeted therapies." (PMID 40071088, 2025). "The combination of DOX and SATB1 shRNA resulted in enhanced inhibition of gastric cancer growth both in vitro and in vivo compared with individual treatments." (PMID 40071088, 2025). "In conclusion, SATB1 plays a pivotal role in the progression, chemoresistance, and metastasis of gastric cancer, positioning it as a potential therapeutic target for improving treatment outcomes in patients with gastric cancer." (PMID 40071088, 2025). "• High SATB1 expression with reduced chemotherapy agent sensitivity; promotes chemotherapy resistance in gastric cancer." (PMID 40071088, 2025). "have employed cationic liposomes to transport SATB1 shRNA for gene therapy in gastric cancer, resulting in the successful inhibition of gastric cancer cell growth." (PMID 37663132, 2023).